KL (klotho)
Diseases named in the same sentence as KL in open-access papers (continued):
Sharing a sentence is not in itself a finding about the gene and the disease.
systemic sclerosis (3 papers, 2017 to 2024). A chronic disorder, possibly autoimmune, marked by excessive production of collagen which results in hardening and thickening of body tissues. "The aim of our study was to evaluate the serum concentration of klotho in a cohort of systemic sclerosis (SSc) patients compared to that of healthy controls and to correlate its levels with the degree and the kind of organ involvement." (PMID 28912623, 2017). "Systemic sclerosis (SSc) is characterized by microvascular damage of skin and internal organs with chronic hypoxia and release of cytokines and hormones such as neutrophil gelatinase-associated lipocalin (NGAL), fibroblast growth factor-23 (FGF-23) and Klotho." (PMID 38777916, 2024).
adenoma (2 papers, 2021). A neoplasm arising from the epithelium. "In KLN mice, we found more small adenomas but there was no significant change in ADC tumorigenesis compared with KL mice (Fig EV2D and E)." (PMID 33439550, 2021).
alcoholic cirrhosis (2 papers, 2022 to 2025). "In contrast, one investigation revealed that alcoholic cirrhosis is associated with elevated levels of α Klotho and FGF-23, which are also linked to abnormal liver function." (PMID 40119098, 2025). "As with the relationship of Klotho with the TNF-α, this result may be interpreted as derived from a compensatory increase of Klotho levels in a context of an increased ROS production (as is the case of alcoholism and, especially, alcoholic cirrhosis)." (PMID 36009045, 2022).
amyloid (2 papers, 2018 to 2022). "The aim of this study was to assess concentrations of Klotho in CSF and plasma and to correlate these findings with KL-VS heterozygosity status to explore a possible association with amyloid and tau burden among a control group of cognitively healthy elderly individuals and patients with AD." (PMID 36413367, 2022). "Therefore, increased elastin fiber in the blood vessel wall and amyloidosis were observed in the tongues of klotho−/− mice compared to klotho+/+ mice." (PMID 28885690, 2018).
apical periodontitis (2 papers, 2022 to 2025). "Collectively, these findings suggest that Klotho may be implicated in the development of periapical periodontitis through the PI3K/Akt/FoxO1 signaling pathway." (PMID 40427517, 2025). "It has been demonstrated that HIF-1α directly activates FGF-23 transcription and Klotho-deficient mice have been shown to exhibit more pronounced bone resorption and delayed healing in a periapical periodontitis model, thereby confirming its anti-inflammatory role in bone repair." (PMID 40427517, 2025). "The apical periodontitis and tooth extraction models generated for this study confirmed the adverse effect of Klotho deletion on tissue repair by mediating both osteoblast and osteoclast activity." (PMID 35538062, 2022). "First, the expression pattern of Klotho was dramatically altered in patients with apical periodontitis." (PMID 35538062, 2022).
Arthritis (2 papers, 2022 to 2024). Inflammation of a joint. "Among the polymorphisms found more frequently in AS patients with arthritis, JAK2 rs7857730, IL-23R rs11209008 and rs10489630, CYP1B1 rs1056836, NELL1 rs8176786, KL rs564481, MEFV rs224204, IL-2RB rs743777, and IL-1A rs1800587 have been described." (PMID 35629038, 2022). "In addition, Klotho has shown promise in predicting mortality in arthritis populations." (PMID 39556550, 2024).
asthma (2 papers, 2017 to 2024). "Airway inflammation and hyperresponsiveness are pathological features of asthma, and Klotho can inhibit the IGF-1 signaling pathway, which leads to reduced proliferation and contraction of airway smooth muscles, decreased airway hyperresponsiveness, and reduced airway resistance." (PMID 38287280, 2024). "Klotho can also inhibit the nuclear translocation of NF-κB and the expression of downstream genes, reducing the release of inflammatory mediators such as interleukin-6 and tumor necrosis factor-alpha, thereby alleviating airway inflammation in COPD and asthma patients." (PMID 38287280, 2024).
autoimmune disease (2 papers, 2023 to 2025). A disorder resulting from loss of function or tissue destruction of an organ or multiple organs, arising from humoral or cellular immune responses of the individual to their own tissue constituents. "Sensitivity analysis between Klotho and autoimmune disease risk." (PMID 40797493, 2025). "Altogether, IFNγ 2, SAMHD1 8 and Klotho 23 have been implicated in autoimmune diseases." (PMID 37213666, 2023). "Klotho is posited to exert a pivotal influence on autoimmune diseases (AIDs)." (PMID 40797493, 2025).
breast tumors (2 papers, 2016 to 2024). "Repeated low-dose injections of Klotho (10 μg/kg) significantly inhibited the growth of breast tumors in mice, and Klotho was well tolerated." (PMID 39329104, 2024). "Together, our results demonstrate that γKlotho is overexpressed in a subset of TN breast tumors where Klotho and βKlotho are downregulated." (PMID 26556877, 2016).
calcinosis (2 papers, 2017 to 2021). Deposition of calcium in the tissues. "A deficiency in klotho expression could be responsible for microangiopathy, calcinosis, and fibrosis, which represent hallmarks of SSc." (PMID 28912623, 2017). "Similarly, patient 7, who had normal pulp morphology, did not have a GALNT3 or FGF23 mutation, and did not have findings consistent with a KLOTHO mutation, had classic calcinosis findings, a markedly elevated cFGF23, and a blood phosphate that was at the upper limit of the normal range." (PMID 33977199, 2021).
cardiac ischemia (2 papers, 2022 to 2025). "Klotho treatment significantly reduced the increase in the levels of circulating HMGB1 in blood at 4 h after myocardial ischemia." (PMID 35453645, 2022). "In addition, recombinant Klotho treatment countered inflammation and cell death induced by permanent cardiac ischemia, supporting Klotho supplementation as a promising therapeutic strategy to globally prevent the deleterious consequences of IHD after a MI." (PMID 39815421, 2025).
cataract (2 papers, 2017 to 2018). Partial or complete opacity of the crystalline lens of one or both eyes that decreases visual acuity and eventually results in blindness. "Klotho gene family seems to be involved in the susceptibility and development of cataracts." (PMID 29075285, 2017). "In studies performed on cataract models, an age-dependent increased methylation of Klotho’s gene promoters has been detected." (PMID 29075285, 2017).
central precocious puberty (2 papers, 2023 to 2024). "For instance, KL regulates growth hormone (GH) secretion from the pituitary gland and is associated with growth factor 1 (IGF-1) and rapid-onset central precocious puberty (RP-CPP), which may be relevant for female precocious puberty." (PMID 39519156, 2024).
Cirrhosis (2 papers, 2013 to 2023). A chronic disorder of the liver in which liver tissue becomes scarred and is partially replaced by regenerative nodules and fibrotic tissue resulting in loss of liver function. "A recent study showed that the hepatic Klotho expression correlated with cirrhosis (stage 4 fibrosis) in HCC, demonstrating a novel pro-oncogenic function of this protein." (PMID 23840612, 2013).
colitis (2 papers, 2013 to 2025). Inflammation of the colon. "The study reported suppression of Klotho expression in three mice models, including the TNBS colitis model, the IL-10 deficient colitis model, and the immunological model of IBD." (PMID 40119098, 2025).
diabetic cardiomyopathy (2 papers, 2019 to 2024). Diabetic cardiomyopathy is a disorder of the heart muscle in people with diabetes. "It has been demonstrated klotho can suppress inflammation by inactivating NF-κB activation in cardiomyocytes, which make it to be a potential therapeutic agent to treat diabetic cardiomyopathy." (PMID 30778287, 2019). "This review explored the interplay between senescence and macrophages in diabetic cardiomyopathy, specifically focusing on the potential role of GDF-15 and Klotho." (PMID 38672115, 2024).
dry eye (2 papers, 2023 to 2024). "In addition, our previous publication confirmed the dry eye status of the Klotho loss-of-function mutant mice." (PMID 38534403, 2024). "Thus, the Klotho null mutation model can be useful for studying cornea degeneration, encompassing senescent corneal diseases, such as dry eye, Fuchs endothelial corneal dystrophy, and bullous keratopathy." (PMID 38534403, 2024). "Since our data showed that the Klotho mutation leads to a gradual process of LG degeneration from normal status to pathogenesis, the Klotho mutant mouse model appears more suitable for studying dry eye as a human disease model." (PMID 37887038, 2023). "This study investigated whether the Klotho null mutation would lead to a dry eye status and the outcome of LG without Klotho function." (PMID 37887038, 2023). "Because most homozygous Klotho null mutant mice would not survive beyond 10 weeks of age, they may be more suitable for investigating the entire scenario of age-related dry eye in a relatively short time." (PMID 37887038, 2023).
fatty liver disease (2 papers, 2022 to 2023). A reversible condition wherein large vacuoles of triglyceride fat accumulate in liver cells via the process of steatosis. "In addition, some polymorphisms of the Klotho gene have been associated with a protective effect against hepatic steatosis in patients with non-alcoholic fatty liver disease." (PMID 36009045, 2022). "A study using an animal model found that klotho knockout mice were extremely emaciated and significantly reduced fat accumulation in the liver, suggesting that it may play a direct role in the pathophysiology of fatty liver disease." (PMID 37753315, 2023).
frontotemporal dementia (2 papers, 2023 to 2025). Frontotemporal dementia (FTD) comprises a group of neurodegenerative disorders, characterized by progressive changes in behavior, executive dysfunction and language impairment, as a result of degeneration of the medial prefrontal and frontoinsular cortices. "In addition, recent findings indicate reduced expression of the klotho gene in patients with AD and frontotemporal dementia (FTD) compared to older healthy controls, independent of genotype, suggesting a role for Klotho in shared pathways of neurodegeneration." (PMID 41393109, 2025).
Gestational Diabetes Mellitus (2 papers, 2022 to 2024). "In an in vitro model of gestational diabetes mellitus, Klotho was found to be involved in the insulin resistance of trophoblast cells, partially mediated through the IGF1/phosphatidylinositol 3-kinase (PI3K)/Akt/mammalian target of rapamycin (mTOR) pathway." (PMID 38486352, 2024). "Klotho modulates glucose metabolism, and its expression is upregulated in the placentas of women with gestational diabetes mellitus (GDM)." (PMID 38486352, 2024). "The physiological role of this pro-diabetic effect of Klotho in gestational diabetes mellitus is as yet unclear." (PMID 38486352, 2024).
glomerular disease (2 papers, 2022 to 2023). "Together, our data reveal that the glomeruloprotective effects of Klotho is mediated via endocrine actions, which increases its therapeutic potential for patients with glomerular diseases." (PMID 36813870, 2023).
hyperaldosteronism (2 papers, 2016 to 2024). Overproduction of aldosterone by the adrenal glands, which may lead to hypokalemia and/or hypernatremia. "While hyperaldosteronism has been described in various Klotho-deficient mouse models in the literature, we observed no change in plasma aldosterone levels (or its precursors) in zG-Kl-KO mice compared to controls, suggesting a minor effect of zG-specific Klotho on aldosterone production." (PMID 38573585, 2024). "Moreover, vascular calcification facilitated by hyperaldosteronism due to klotho deficiency has also been shown to be mitigated by spironolactone treatment in mice." (PMID 27153999, 2016). "Thereby, our results suggest that while zG-specific Klotho depletion leads to molecular changes indicative of stimulated aldosterone synthesis pathways, these alterations are not sufficient to induce a state of hyperaldosteronism." (PMID 38573585, 2024).
Hypercalciuria (2 papers, 2020 to 2025). "Similarly, a kidney‐specific KO Klotho animal model using a different promoter and standard chow was described with increased serum Ca2+ levels and pronounced hypercalciuria." (PMID 40165603, 2025).
infarct (2 papers, 2017 to 2019). "The knockdown of Klotho mediated by LV-KL shRNA in the brain exacerbated neurological dysfunction and cerebral infarct after 22 h of reperfusion following 2 h middle cerebral artery occlusion in rats." (PMID 29403373, 2017).
insulinoma (2 papers, 2022 to 2025). "There is an abundant expression of Klotho in the insulinoma β cells in mouse pancreatic islets (MIN6 β cells), and its silencing/overexpression significantly reduces/increases glucose-stimulated insulin production in MIN6 β cells." (PMID 36440221, 2022). "Here we showed that pancreatic INS-1 cell (a rat insulinoma cell line commonly used to study pancreatic β-cell function) developed the typical hallmarks of senescent cells when treated with doxorubicin in vitro, and this was accompanied by downregulation of endogenous KL expression." (PMID 40018267, 2025).
intrauterine growth restriction (2 papers, 2024 to 2025). "In cases of intrauterine growth restriction (IUGR), the expression of Klotho protein in maternal venous blood, umbilical cord blood, and placental tissue are reduced, accompanied by changes in GH, IGF-1, and IGFBP." (PMID 40831795, 2025).
invasive carcinoma (2 papers, 2010 to 2020). A carcinoma that is not confined to the epithelium, and has spread to the surrounding stroma. "Frequent (41%) promoter methylation of KLOTHO occurred in invasive carcinoma but not in normal cervical tissues or during the early, preinvasive phase of primary cervical tumors." (PMID 20482749, 2010).
kidney transplant (2 papers, 2025 to 2026). A surgical procedure in which one or both kidneys from a donor are implanted into a recipient. "This study aimed to evaluate the levels of FGF23, Klotho, IL-6, IL-10, and Mstn in relation to subjects without comorbidities in stable kidney transplant recipients receiving triple immunosuppressive therapy." (PMID 41303166, 2025).
liposarcoma (2 papers, 2018 to 2020). A usually painless malignant tumor that arises from adipose tissue. "Indeed, we observed that a higher KL expression in liposarcomas is associated with a better outcome for patients." (PMID 30441794, 2018). "Through the analysis of publicly available data, significant downregulation of Klotho mRNA expression in 61 dedifferentiated liposarcomas (DDLPS) compared with 49 adipose tissue controls was detected." (PMID 32585905, 2020). "Moreover, KL is downregulated in dedifferentiated liposarcomas (DDLPS) compared to well-differentiated tumors and adipose tissue." (PMID 30441794, 2018).
liver disease (2 papers, 2022 to 2025). "There is little information available on the connection between Klotho and liver disease." (PMID 40119098, 2025).
lupus nephritis (2 papers, 2020 to 2023). Glomerulonephritis in the context of systemic lupus erythematosus. "Collectively, our findings support the protective role of Klotho in attenuating lupus nephritis through the inhibition of IFNγ-induced SAMHD1 expression and IFNγ downstream signaling in MES-13 cells." (PMID 37213666, 2023). "Little information exists regarding the effect of Klotho in lupus nephritis, one of the prevalent symptoms of SLE." (PMID 37213666, 2023). "miR-199a has also been reported to be involved in inflammation via modulating the activation of NF-κB by targeting Klotho in lupus nephritis." (PMID 31979395, 2020). "Little information exists regarding the effect of Klotho in lupus nephritis." (PMID 37213666, 2023). "Our results indicated that the participation of Klotho in lupus nephritis may be partially attributed to its inhibitory effect on IFNγ-induced SAMHD1 expression and NFκB activation in MES-13 cells." (PMID 37213666, 2023). "The present study verified the effect of IFNγ on SAMHD1 and Klotho expression in MES-13 glomerular mesangial cells, a special cell type in glomerulus that is critically involved in lupus nephritis." (PMID 37213666, 2023).
lymph node metastasis (2 papers, 2020 to 2024). "KL and KC bi-mutational status correlated significantly with lymph node metastasis, as all (16/16) of the KL tumors and all but one (20/21) KC tumors were associated with lymph node metastasis 8.5% (16/188) and 10% (20/188) vs. 0% (0/60) and 1.7% (1/188) (p = 0.015) and (p = 0.03), respectively." (PMID 38791897, 2024). "Others found an association of KL expression with decreased survival of CRC patients or TNM stage, invasiveness, and lymph node metastasis." (PMID 33520985, 2020). "Moreover, KL expression is inversely correlated with invasion depth, histological grade, clinical stage, and lymph node metastasis in esophageal SCC." (PMID 33520985, 2020).
multiple myeloma (2 papers, 2015 to 2017). "Klotho immunostaining was seen in plasma cells in all myeloma cases." (PMID 25944690, 2015). "However, the level of serum soluble Klotho was unchanged in multiple myeloma." (PMID 28153033, 2017). "FGFRs are abundantly expressed in MM, but klotho has not been reported in myeloma cells, which we next tested." (PMID 25944690, 2015).
muscle atrophy (2 papers, 2024 to 2025). The loss of muscle tissue due to inactivity or disease. "Systemic soluble Klotho concentrations are suppressed with aging and associated with muscle atrophy." (PMID 40869307, 2025).
non-small cell lung carcinoma (2 papers, 2020 to 2022). A group of at least three distinct histological types of lung cancer, including non-small cell squamous cell carcinoma, adenocarcinoma, and large cell carcinoma. "Inhibition of miR-10b has been shown to restore Klotho expression in models of non-small cell lung cancer." (PMID 32585905, 2020).
oral cancer (2 papers, 2022 to 2025). "Moreover, a meta-analysis including 18 studies conducted in 2018 showed that lower klotho was associated with oral malignancy (OR: 0.034; 95% CI: 0.002, 0.630), indicating its function as a biomarker in oral cancer." (PMID 36204099, 2022). "Further clarifying the interaction mechanism between Klotho and NNMT in oral cancer may provide a theoretical basis for novel targeted therapeutic strategies, thereby improving the clinical predicament of poor prognosis for oral cancer patients." (PMID 40427517, 2025).
oral diseases (2 papers, 2022 to 2025). "Evaluation of the clinical feasibility of Klotho as a diagnostic biomarker and therapeutic target for oral diseases." (PMID 40427517, 2025). "This section is dedicated to delineating the molecular regulatory characteristics and underlying mechanisms of Klotho in oral diseases, thereby providing novel perspectives for targeted therapeutic interventions." (PMID 40427517, 2025). "Further studies are necessary to clarify the potential mechanisms and demonstrate the predictive ability of klotho in oral diseases." (PMID 36204099, 2022). "Thus, more animal experiments and clinical trials are necessary to validate the therapeutic effects and safety of Klotho in various oral diseases, as well as to assess its feasibility for clinical translation." (PMID 40427517, 2025).
oral squamous cell carcinoma (2 papers, 2020 to 2025). "Lower KL and higher DNA methyltransferase 3a (enzyme required for epigenetic alteration of KL promoter activity) are typical of the transition from normal tissue to oral dysplastic lesions to oral squamous cell carcinoma (SCC)." (PMID 33520985, 2020).